KRT16 (keratin 16)
Diseases named in the same sentence as KRT16 in open-access papers (continued):
Sharing a sentence is not in itself a finding about the gene and the disease.
nevus (1 paper, 2020). Nevus (or naevus, plural nevi or naevi, from nævus, Latin for "birthmark") is the medical term for sharply circumscribed[1] and chronic lesions of the skin or mucosa. "It suggested that significantly elevated FABP5, IVL, KRT6A, KRT15, KRT16, and TIMP2 proteins expressed in the CM than in the nevus tissues." (PMID 32934956, 2020). "Next, to validate differential expressions of six prognostic hub genes between CM tissues and nevus tissues, we performed IHC analysis and found significantly elevated FABP5, IVL, KRT6A, KRT15, KRT16, and TIMP2 protein expressions in the CM than in the nevus tissues." (PMID 32934956, 2020).
Oral leukoplakia (1 paper, 2024). A thickened white patch on the oral mucosa that cannot be rubbed off. "The KRT16 p.L132P mutation was significantly associated with younger age of onset, the presence of palmar keratoderma oral leukokeratosis, and a higher number of involved nails." (PMID 39606016, 2024). "PC is a rare autosomal dominant genetic skin disorder that is divided into two subtypes: PC-1 (Jadassohn–Lewandowski type) and PC-2 (Jackson–Lawler type), in which PC-1 is caused by mutations in KRT6A or KRT16 and is characterized by oral leukoplakia." (PMID 39606016, 2024).
pancreatic diseases (1 paper, 2021). "Some of them were upregulated in patients with other pancreatic diseases, such as HBB, HBA1, and KRT16 proteins, while some were upregulated only in PC groups (i.e. ALIX, GPRC5B, SDCBP, and IST1), highlighting their potential diagnostic value." (PMID 34026608, 2021).
rosacea (1 paper, 2025). A chronic erythematous skin disorder that affects the face. "Compared with healthy controls, KRT6A and KRT16 mRNA levels were significantly upregulated in rosacea, whereas CLDN1, CLDN16, OCLN, and KRT17 showed no significant changes, and CLDN23 was significantly downregulated." (PMID 40346694, 2025).
triple-negative breast carcinoma (1 paper, 2017). An invasive breast carcinoma which is negative for expression of estrogen receptor (ER), progesterone receptor (PR), and human epidermal growth factor receptor 2 (HER2). "Overexpression of KRT16 mRNA has been identified as a prognostic markers in triple negative breast cancer." (PMID 28418924, 2017).
urothelial carcinoma (1 paper, 2022). A malignant neoplasm derived from the transitional epithelium of the urinary tract (urinary bladder, ureter, urethra, or renal pelvis). "Cytokeratin 16 has been associated with ureter, bladder and urethra and also keratinization of urothelial carcinomas." (PMID 35439943, 2022).
vitiligo (1 paper, 2022). Generalized well circumscribed patches of leukoderma that are generally distributed over symmetric body locations and is due to autoimmune destruction of melanocytes. "Again, KRT6A- and KRT16-expressing cells were found in healthy and nonlesional acute vitiligo skin, but these populations did not express CXCL9/10." (PMID 35653192, 2022). "While some keratinocytes in the active vitiligo data set expressed stress keratins (KRT6A, KRT16), they were mainly derived from healthy and nonlesional skin." (PMID 35653192, 2022).
tumor (39 papers, 2009 to 2026). "In NSCLC, KRT16 was up-regulated, and its high levels were associated with advanced tumor stage, lymph node metastasis, and poor prognosis." (PMID 42037661, 2026). "Circulating tumor cells (CTCs) expressing KRT16 are also associated with shorter relapse-free survival." (PMID 40909564, 2025). "In metastatic breast cancer patients, circulating tumor cells expressing keratin 16 were associated with shorter relapse-free survival." (PMID 34359774, 2021). "In in silico analysis, high expression of keratin 16 was associated with higher tumor aggressiveness." (PMID 34359774, 2021). "Mutations in KRT6 are associated with hereditary skin diseases, and KRT16 contributes to the immune response to tumors and in tumor cell development." (PMID 32934956, 2020). "The up-regulation of KRT16 has been associated with higher tumor aggressiveness, acting as a positive regulator of cellular motility by reorganizing the actin cytoskeleton and in circulating tumor cells of metastatic breast cancer patients, associated with shorter relapse-free survival." (PMID 40429863, 2025). "Thereafter, we detected an elevated expression of several tumor cell‐associated markers, including S100P, KRT17, KRT16, KRT7, and LY6D, as previously reported." (PMID 41164952, 2026). "Increased expression of keratin 6A and the involvement of keratin 16 in the development of this type of tumor have also been reported in LUAD." (PMID 39194725, 2024). "Keratin 16 has also been reported to promote tumor progression and metastasis by inducing epithelial-to-mesenchymal transition (EMT), as has been demonstrated in LUAD and MCF-7 cells." (PMID 39194725, 2024). "Immunohistochemical detection of KRT16 and ki67 in tumor tissues demonstrated that the expression of KRT16 and Ki67 was reduced in xenograft tumors from mice injected with oe-BARX2." (PMID 35037835, 2022). "This is an important issue for future research to determine the exact function of keratin 16 in tumor dissemination and metastasis development by analyzing keratin 16 status in disseminating tumor cells." (PMID 34359774, 2021). "To determine if KRT16 promotes tumor progression by regulating integrins and their signaling, we examined the expression level of integrin isoforms in KRT16-depleted OSCC cells." (PMID 30782177, 2019). "The sole exception among the basal markers was for one tumor (Cd#2) which showed weaker staining for KRT16." (PMID 30550540, 2018). "KRT16 showed the lowest number of stained tumor cells, with between 5 and 50% of the cells showing staining." (PMID 30550540, 2018). "In agreement with the columnar differentiation displayed by all these tumours, the expression of Krt16 and other squamous markers such as p63 and Krt14 (data not shown) was never detected." (PMID 29700411, 2018). "Immunohistochemical localization showed that KRT1, KRT6, and KRT16 were highly elevated in the well-differentiated cells in the center of the tumor rests when compared to the less differentiated cells at the periphery." (PMID 30550540, 2018). "KRT16 staining was present in both cytoplasm and nucleus of the normal ductal epithelia and tumor cells." (PMID 28418924, 2017). "The average H-score for KRT16 expression was 236.1 ± 46.8 in tumors and 135.8 ± 56.8 in non-tumor tissues, respectively (P = 0.002)." (PMID 28418924, 2017). "A higher expression of KRT16 was observed in tumor than its adjacent normal pancreatic tissue in our study." (PMID 28418924, 2017). "We identified 9 genes whose increased expression was significantly associated with tumor size in female LC patients of which four code for MAPK signaling molecules (DUSP4, FGL1, TXNRD1, PLA2G4E), three for oncogenes (KRT16, STRIP2 and TNS4), tumor suppressor cystatin 5, and NQO1." (PMID 38245882, 2024). "Keratin 16, in particular, has been identified as a marker for circulating tumor cells." (PMID 39194725, 2024). "Expression of S100A7 and KRT16 was rarely detected in the tumor mass." (PMID 38892279, 2024).
tumor (continued). "We found that keratin 16 was upregulated in most of the HPV- tumor cells." (PMID 35769468, 2022). "The Epi1 program was characterized by the expression of stress keratins (KRT6, KRT16, and KRT17) that are associated with keratinocyte hyperproliferation and therefore may play a role in enhancing tumorigenesis and tumor growth." (PMID 34489433, 2021). "In addition, KRT16 contributes to the immune response to tumors and in tumor cell development." (PMID 33441834, 2021). "Our staining results of 190 samples show that expression of GLI1, GLI3, KRT16, and S100A7 was mostly detected in the epidermal layer overlying or bordering the tumor mass." (PMID 38892279, 2024). "We suggest further examination of KRT16 and S100A7, especially since S100A7 showed a statistically significant trend regarding tumor staging and staining intensity." (PMID 38892279, 2024). "The tumor mass itself was found positive for GLI1 and GLI3 in a proportion of samples, while S100A7 and KRT16 were rarely detected." (PMID 38892279, 2024). "We show that staining of GLI1, KRT16, and S100A7 appears in the same places in the samples (same samples and different tumor slices) in all stages, while the localization of staining of GLI3 differs from the other proteins at lower stages." (PMID 38892279, 2024). "We selected four markers that were differentially expressed in normal and tumor human lung tissues: CADM1, KRT16, MMP1, and NAPSA." (PMID 38067281, 2023). "The differential expression between tumor and adjacent tissues expression levels displayed for KRT14, KRT16, KRT17, and KRT6B indicated that their expression levels were higher in normal tissues than in tumors." (PMID 36293530, 2022). "The differential gene expression levels between tumor and adjacent tissue displayed in the box plot showed that LAMB3, KRT14, KRT16, KRT17, and KRT6B expression levels were significantly (p < 0.001) higher in normal tissues than in tumors." (PMID 36293530, 2022). "LAMC2, an isoform of the laminin family, and the KRT14, KRT16, and KRT17 hemi-desmosomal proteins play crucial roles in tumor cell stability and filament formation anchorage, migration, and proliferation." (PMID 32922662, 2020). "FABP5, IVL, KRT6A, KRT15, KRT16, and TIMP2 expression profiles suggested relatively significant elevated expression in tumor tissues compared with the corresponding normal tissues." (PMID 32934956, 2020). "In this study, we found upregulation of KRT16 in highly invasive OSCC lines and in OSCC tumor tissues." (PMID 30782177, 2019). "KRT1, KRT6, KRT16 and KRT17 showed strong staining in the well-differentiated cells in the center of the tumor nests when compared to the staining in the peripheral tumor cells." (PMID 30550540, 2018). "Specifically, the level 3 classifier shows strong correlations among genes like KRT5, S100A7, KRT16, S100P, and LY6D, while the level 6 classifier exhibits similar patterns with GPR17, RGR, and NPPA, highlighting the complex interplay of genes in tumor subtype classification." (PMID 40802546, 2025). "Consistent with RNA-seq data, the expression of SLN, TAC1, MYH8, and PGAM2 were down-regulated, whereas SDRC7, KRT16, S100A9, IL36G, and FABP9 were up-regulated in both blood (Animal #9, #11, and #12) and skin (Animal #6, #7, and #8)-induced tumours relative to normal skin controls." (PMID 31340720, 2019). "Among the 17 overexpressed genes, CDX1 (caudal type homeobox 1) had the highest fold difference in tumor versus non-tumor tissues followed by SI (sucrase-isomaltase, aka alpha-glucosidase), KRT16 (keratin 16) and SERPINB5 (serpin peptidase inhibitor, clade B (ovalbumin), member 5)." (PMID 28418924, 2017). "Tumor tissues showed a significantly higher level of KRT16 expression than non-tumor tissues, especially in cytoplasm." (PMID 28418924, 2017).
tumor (continued). "Among the 17 upregulated genes, we selected the top five, i.e. CDX1, SI, KRT16, HOXA10, and SERPINB5 for validation using RT-PCR in the 20 pairs of tumor and non-tumor tissues that were not used in RNA-seq." (PMID 28418924, 2017).
cancer (31 papers, 2006 to 2025). A tumor composed of atypical neoplastic, often pleomorphic cells that invade other tissues. "Moreover Keratin 16 overexpression has already been demonstrated linked to increase cell migration in cancer." (PMID 35350386, 2022). "Previously we have shown by in silico analysis that keratin 16 (KRT16) mRNA upregulation might be associated with more aggressive cancer." (PMID 34359774, 2021). "A recent pan-cancer study identified KRT16 as one of the proteins with the highest correlation in expression with S100A7." (PMID 38892279, 2024). "We employed real-time quantitative reverse transcription polymerase chain reaction (qRT‒PCR) to assess the expression levels of three biomarkers, vimentin, KRT16, and KRT18, associated with metastasis and EMT in cancer cells following a 48-h hypoxia treatment." (PMID 37780810, 2023). "Our results confirmed that hypoxia treatment upregulated the expression of vimentin and KRT16 while downregulating the expression of KRT18 in both cancer cell types, indicating the upregulation of EMT and metastasis." (PMID 37780810, 2023). "In fact, the miR-365-3p/KRT16 signaling also pertains the ability to regulate cancer stemness and drug resistance via interaction with the β5-integrin/c-Met pathway in promoting tumorigenesis of OSCC." (PMID 35706019, 2022). "We also found that depletion of KRT16 lead to decreased migration, invasion, metastasis, and cancer stemness in OSCC cells." (PMID 30782177, 2019). "Taken together, depletion of KRT16 impaired migration, invasion, metastasis, and cancer stemness of OSCC cells." (PMID 30782177, 2019). "Taken together, our study unveiled a novel miR-365-3p/EHF/KRT16/β5-integrin/c-Met signaling axis regulating metastasis, cancer stemness, and drug resistance in OSCC." (PMID 30782177, 2019). "It is possible that the ATF4 regulation of KRT16 is inhibited in normal cells, but is somehow activated during cancer progression processes." (PMID 29420561, 2018). "Keratin 16 is an epithelial protein highly expressed at pressure bearing sites and during wound healing and cancer." (PMID 28128203, 2017). "KRT16 mRNA increases in 16E6E7-expressing HFKs may be dampened in more advanced cancer cells or as a result of one of the other HPV16 genes." (PMID 34944802, 2021). "To evaluate whether KRT16 promotes cancer cell metastasis in vivo, we employed an experimental metastasis model via tail vein injection of OSCC cells in CB17-SCID mice." (PMID 30782177, 2019). "Critical genes like KRT16 and KRT17 played central roles across these different analytical platforms, underscoring their significance in cancer molecular dynamics." (PMID 40725485, 2025). "Critical hub genes, including KRT16, KRT17, CST1, and CRABP2 emerged as central nodes with high connectivity across multiple cancer-related pathways in both datasets." (PMID 40725485, 2025). "Recently, altered expression of several keratins including keratin 6 (KRT6), KRT14, KRT15, KRT16, KRT17 and KRT19 were reported to coordinate tumorigenesis in different types of cancers." (PMID 35706019, 2022). "The top three proteins, KRT16 (with a fold change of 45.6), CFHR4 (with a fold change of 41.2), and CFHR1 (with a fold change of 27.9), all displayed higher plasma levels in samples from patients with stage III cancer in the right colon than the rectum." (PMID 32452655, 2020). "Furthermore, we unveiled the novel miR-365-3p/EHF/KRT16/β5-integrin/c-Met pathway capable of regulating OSCC cell migration, invasion, metastasis, and cancer stemness by activation of the Src/STAT3 signaling." (PMID 30782177, 2019). "The results suggest a conditional regulation of KRT16 gene by ATF4 that may be inhibited in normal cells, but engaged during cancer progression." (PMID 29420561, 2018).
cancer (continued). "Levels of keratins, type I cytoskeletal 16 (KRT16), 9 (KRT9), and 10 (KRT10), as well as complement factor H‐related protein 4 (CFHR4) and 1 (CFHR1), had higher levels in plasma samples from patients with cancer in the right colon (with fold changes between 6.2‐13.0)." (PMID 32452655, 2020). "The failure to induce KRT16 mRNA in HaCaT and HEK293T cells, as opposed to the robust induction in HCT116 and HeLa cells may be explained by certain steps during cancer progression and selection of cells that are more competitive in tumors." (PMID 29420561, 2018). "Our results indicate that although KRT16 gene contains a functional ATF4-responsive DNA element, its regulation by ATF4 is conditional, and in particular, the gene responds to ATF4 in the two patient-derived cancer cell lines, but not in the cell lines transformed in vitro." (PMID 29420561, 2018).
infection (7 papers, 2015 to 2026). The state of being infected such as from the introduction of a foreign agent such as serum, vaccine, antigenic substance or organism. "KRT16 levels were significantly elevated in patients aged 21-40 and were associated with Helicobacter pylori infection." (PMID 42037661, 2026).
KRT16 also shares sentences with these, for which no sentence is quoted: epidermal disease (3 papers); Erythema (3); adenocarcinoma (2); bladder tumor (2); cholesteatoma (2); diabetic foot ulcer (2); epidermolytic hyperkeratosis (2); gastric cancer (2); Nail dystrophy (2); Obesity (2); staphylococcus aureus infection (2); ulcer (2); actinic keratosis (1); adenoid cystic carcinoma (1); Alzheimer disease (1); amyloid (1); Autoimmunity (1); autosomal recessive congenital ichthyosis (1); basal cell carcinoma (1); bladder urothelial carcinoma (1); Bowen’s disease (1); breast invasive carcinoma (1); cervical squamous cell carcinoma (1); chronic periodontitis (1); common wart (1); contact dermatitis (1); Crohn disease (1); cutaneous melanoma (1); discoid lupus erythematosus (1); dry eye (1).
A further 40 diseases each share a sentence with KRT16 in 1 paper.